COL1A1 (collagen type I alpha 1 chain)
Diseases named in the same sentence as COL1A1 in open-access papers (continued):
Sharing a sentence is not in itself a finding about the gene and the disease.
cancer (continued). "LYZ is associated with neutrophil degranulation and host defense peptides, whereas COL1A1, COL1A2 along with HGF, TNC, and VEGFA are all part of the PI3K pathway, which plays an important role in cancer progression, and has been implicated in TNT regulation." (PMID 37955637, 2023). "The miR-29 family negatively regulates collagen expression by directly targeting COL1A1’s and COL1A2’s mRNA transcripts, while the other miRNAs are linked to fibrosis and cancers, suggesting their effect on the synthesis of the ECM." (PMID 37895885, 2023). "In the context of cancer, miR-126-5p and miR-218-5p were predicted and confirmed to downregulate COL1A1 mRNA levels through binding sites in its 3′ untranslated region." (PMID 37373151, 2023). "RUNX2 overexpression induced COL1A1 expression and promoted cancer cell migration and invasion in vitro and in an animal model of metastasis via COL1A1." (PMID 37108164, 2023). "Our network-based framework identified common invasiveness-associated MRs specific to INV-H and INV-L groups across the ten prognostic cancers, including COL1A1, which is also part of the 24-gene signature, thus acting as a positive control." (PMID 37599366, 2023). "We found that all the fibroblast clusters showed a high expression of the well-defined panCAF markers including COL1A1, DCN, VIM, FAP, and PDPN4, indicating the identified fibroblasts are likely cancer-associated fibroblasts (CAFs)." (PMID 37612267, 2023). "As collagen type I is the dominant collagen, often highly secreted by fibroblasts and stroma cells, COL1A1 is positively correlated with the stroma fraction in all but 3 of the cancer types." (PMID 37414817, 2023). "To further confirm functional proteins associated with drug efficacy and response, we identified 19 genes as cancer-related genes (CRGs) in PCa, whereas 15 were overlapped DEP/Gs, and four (TTN, NBPF14, AHNAK2, COL1A1) were the top mutated genes in PCMR." (PMID 37121942, 2023). "Previously, other studies proposed COL1A1, COL1A2, and COL4A1 as candidate diagnostic markers for this cancer." (PMID 38041130, 2023). "The results reveal that the expression of COL1A1 has a strong correlation with the TME of various cancers." (PMID 35789341, 2022). "High expression of COL1A1 can predict the prognosis of cancer and is a reliable biomarker and therapeutic target." (PMID 36313300, 2022). "Patients with high percentage of cancer associated fibroblasts and expression of TIMP3 but low expression of COL1A1, COL3A1, MMP1 and POSTN were associated with sensitivity to paclitaxel." (PMID 35480306, 2022). "The outcome indicates that highly expressed COL1A1 is significantly related to the poor prognosis of these cancers." (PMID 35789341, 2022). "What's more, it is well known that PI3K-Akt signaling pathway (COL1A2, COL1A1, etc.)plays a vital role in the cell cycle and is activated in various cancers, including GAC." (PMID 35726219, 2022). "We find that COL1A1 has higher expression levels in multiple cancer tissues and the highly expressed COL1A1 is closely correlated to the poor prognosis of LGG." (PMID 35789341, 2022). "The COL1A1 gene is the main component of the extracellular matrix and has been reported in many cancers." (PMID 35645616, 2022). "Fibro_2 cells were characterized by collagen (COL1A1, COL3A1) and cancer-associated fibroblast genes (CTHRC1, FAP)." (PMID 35935940, 2022). "EA restored BM hematopoiesis despite the effects of cancer and chemotherapy by regulating type I collagen α1 chain (Col1a1)." (PMID 34552585, 2021). "Increased COL1A1 expression has been observed in cancer cells, and collagen type I contributes to the differentiation and metastatic abilities of human cancer cells." (PMID 35008515, 2021). "Cluster 0 cells showed fibroblast signatures (RGS5 and NDUFA4L2), cluster 2 cells had strong expression of cancer associated fibroblast (CAF) markers (LUM, SFRP4, and COL1A1), and cluster 5 cells expressed myofibroblast markers (MYH11, TAGLN, and ACTA2)." (PMID 33662621, 2021).
cancer (continued). "COL1A1 is known to be overexpressed in several cancers other than gastrointestinal cancers, such as thyroid cancer, lung cancer, breast cancer, and renal cancer." (PMID 34395525, 2021). "We have identified, through IHC, a gradient of expression of COL1A1 gradually decreasing from cancer tissue to distant mesenteric pAT and a gradual modification in COL1A1 spatial arrangement." (PMID 33670920, 2021). "Many important components of ECM, which were differentially expressed in cluster 1 or 2, such as COL6A1, COL1A1, and COL3A1, are mainly secreted by cancer-associated fibroblasts (CAF)." (PMID 33508502, 2021). "We have identified, through IHC, a gradient of expression of COL1A1, more abundant in cancer tissue compared to normal distant sites, supporting its role in migration." (PMID 33670920, 2021). "From the gene expression results, we observed that the amount of COL1A1 increased in cancer tissue compared to COL3A1." (PMID 34771715, 2021). "Among them, collagen family Col1a1, Col4a2 and Col5a1 are target genes of miR-29a-3p, and promote cancer cells invasion and migration." (PMID 34135859, 2021). "Yet, the mapped genes were highly relevant to PCa etiology and included known cancer drivers LDLRAD4, GMNN, COL1A1, CD38, PTPRN2, GTSE1 and CAMK2N1 in the risk signature and KLK2, AR, KLK3, SPDEF in the relapse signature." (PMID 33845808, 2021). "COL1A1 has been considered as an oncogene and promoted cancer migration and invasion by inducing epithelial-mesenchymal transition." (PMID 32850407, 2020). "Known cancer genes such as COL1A1 or STK11 were affected by duplications and other known genes such as CDKN2A, JAK2, PRDM1, FBXW7, or GOLGA5 were affected by deletions in several tumors of this subcluster." (PMID 32604718, 2020). "Cancer‐associated fibroblasts (CAFs), expressing extracellular matrix (ECM) genes such as COL1A1, LUM, and BGN, formed the larger cluster." (PMID 33332768, 2020). "The dysregulation of COL1A1 and COL1A2 is thought to be associated with changes in the extracellular matrix (ECM) and the subsequent metastasis of cancer cells." (PMID 32612946, 2020). "In this cluster, Rac Family Small GTPase 1 (RAC1), Caveolin 1 (CAV1), Low-density lipoprotein receptor-related protein 6 (LRP6) and collagen type I alpha 1 chain (COL1A1) were identified as proteins shown to promote EMT in various cancer." (PMID 33050615, 2020). "Group comparison revealed that high COL1A1 mRNA expression was significantly correlated with advanced clinical stages and increased with the progression of carcinoma." (PMID 32612946, 2020). "There is evidence of the involvement of members of the collagen family in carcinogenesis in several tissue types, and aberrant expression of COL1A1 and COL1A2 has been implicated in some cancers." (PMID 31181620, 2019). "Our data suggest a model through which cancer-derived miR-218 inhibits osteoblast function of collagen deposition though direct targeting of collagen type I alpha 1 chain (COL1A1) and regulation of inhibin βA expression." (PMID 30348200, 2018). "Recent studies have indicated overexpression of COL1A1 as an important event in a series of cancers." (PMID 28775672, 2017). "Obviously, COL1A1 was expressed at substantially higher levels in the cancer samples by contrast to the weak but detectable expression in normal tissues with a statistical significance (P < 0.05)." (PMID 28775672, 2017). "Our results demonstrated that COL1A1 expression was significant elevated in almost cancer tissues compared to adjacent normal tissues (P < 0.05)." (PMID 28775672, 2017). "PRL and mammographic density are epidemiologically linked and PRL enhances the expression of mammary ECM components such as Col1a1, and Tnc, which promotes cancer cell invasion." (PMID 28103936, 2017). "The downregulation of COL1A1 on RCSC treatment points to inhibition of cancer cell progression and possibility of angiogenesis." (PMID 27806706, 2016).
cancer (continued). "The second is collagen 1a1 (COL1A1), which is an important regulator of pro-metastatic processes in cancer." (PMID 26569312, 2015). "Another interesting pathways activated in both cancer cell lines is the extracellular matrix organization which involves up-regulation of different collagen genes like (COL1A1, COL1A2, COL3A1), and matrix metallopeptidase like (MMP8, MMP14)." (PMID 25077705, 2014). "B4GALNT2, SLC9A2 and COL1A1 were significantly altered in carcinoma compared to normal or adenomatous polyp tissue." (PMID 25423035, 2014). "Collagen type I alpha 1 (COL1A1), a member of the collagen family, is primarily expressed in the extracellular matrix (ECM) and serves as both a diagnostic and prognostic marker in various cancers." (PMID 40851082, 2025). "ITGB1 is the molecule that mediates COL1A1 in the invasion and migration of cancer cells." (PMID 38963646, 2025). "UMAP dimensionality reduction and clustering identified distinct cell populations, including monocytes, B cells, NK cells, T cells, macrophages, cancer stem cells, epithelial cells, and endothelial cells, with COL1A1 predominantly expressed in cancer stem cells." (PMID 40851082, 2025). "Additionally, collagen degradation products, particularly those involving COL1A1 and COL1A2, can influence the epithelial-mesenchymal transition, a process associated with increased migratory and invasive capabilities of cancer cells." (PMID 40216311, 2025). "Additionally, the ECM, with components like collagen1A1 (COL1A1), plays a crucial role in both protecting cancer cells and modulating drug response." (PMID 40282535, 2025). "In the present study, COL1A1 silencing in KIRC cells was associated with reduced expression of the stemness markers OCT4 and SOX2, supporting a possible involvement in the maintenance of cancer stem cell properties." (PMID 40851082, 2025). "Furthermore, COL1A1 is highly expressed in various cancers and regulates various cellular processes, including cell proliferation, metastasis, and apoptosis." (PMID 38612943, 2024). "Moreover, we verified that RT triggered an increase in the expression of COL1A1 and α‐SMA in cancer‐associated fibroblasts (CAFs)." (PMID 38704675, 2024). "Research has demonstrated the significance of COL1A1 in different cancers." (PMID 38913913, 2024). "In addition, this panel includes ECM components that stimulate cancer cell invasion, such as collagens (e.g., COL1A1, COL4A1), the extracellular matrix glycoproteins laminins (e.g., LAMA1, LAMC1), fibronectin (FN1), and SPARC, among others." (PMID 38437557, 2024). "More recently, researchers have increasingly focused on the role of COL1A1 in cancer." (PMID 39845977, 2024). "In recent years, COL1A1 has been shown to be highly expressed in a variety of cancers." (PMID 38979664, 2024). "Using scRNA-seq data, we investigated the expression of genes involved in stromal-like signature (FAP, VIM, and ITGB1); cancer-associated fibroblasts (CAFs; POSTN and ACTA2); as well as COL1A1, SULF1, TCF21, and DLK1, which were previously associated with FAP-high or FAP-low CAF phenotypes in OC." (PMID 39634630, 2024). "This has made COL1A1 a focal point in cancer biology research." (PMID 39845977, 2024). "Additionally, validation using the HPA database confirmed an increase in COL1A1 mRNA expression in several cancers, although its specificity to cancer types was relatively low." (PMID 39845977, 2024). "In addition to COL1A1 and BGLAP, the other six genes in the signature have been reported to be associated with cancers in both basic and clinical studies." (PMID 37564213, 2023). "COL1A1 is a published biomarker and potential therapeutic target of ER + cancers." (PMID 36598637, 2023). "COL1A1 is closely related to the occurrence of malignant tumors." (PMID 37684969, 2023). "The cancer-associated LR interactions in immune-to-fibroblast subset identified high number of CD44 and VIM receptors interacting with COL1A1 and ITGB1_COL1A2 for the HGSOC histotype." (PMID 38328306, 2023).
cancer (continued). "Importantly, COL1A1 was recently identified as a candidate biomarker for HNSCC and associated with cancer stem cell signature in HNSCC." (PMID 37455825, 2023). "Moreover, we determined that the two regulators acted as the pan-cancer fitness gene 21, and DepMap data also reminded that COL1A1 and BGLAP were essential genes in almost all cancer types." (PMID 37564213, 2023). "Functional analysis indicated that the highly-expressed FAP in these cancers could affect extracellular matrix organization process and interacted with genes like COL1A1, COL1A2, COL3A1 and POSTN." (PMID 37325617, 2023). "The high-throughput proteomics analysis revealed differential expressions of Acsl1, Plin1, Dbil5, Plin4, Col12a1, Col1a1, Col5a3, Col1a2, and Dcn, which are associated with the PPAR signaling pathway, protein digestion and absorption, and the protein glycan pathway in cancer." (PMID 36874004, 2023). "Notably, as expected, the COL1A1+/COL1A2+/IGFBP2+ fibroblast-like cells especially MSC-like-c2 present strong interactions with malignant tumor cells (MTC), which confirms our observation from in-house data." (PMID 37479733, 2023). "As expected, we identified that the upregulation of three collagen genes (COL1A1, COL3A1, and COL1A2), BTG2, and JUNB might be responsible for the radiation-associated secondary cancers in patients with BCa." (PMID 35274048, 2022). "In more detail, we found collagen (COL) 1A1 and COL1A2 as one of the most significant up-regulated genes in BM which is in line with previous studies reporting COL1A1 and COL1A2 to be associated with an aggressive and pro-metastatic phenotype in diverse cancer types." (PMID 36361816, 2022). "Stromal cells (or cancer-associated cells) included endothelial cells (PECAM1/CD31+ and MMRN1+), fibroblasts (COL6A1+, COL1A1+, THY1+, and DCN+), epithelial cells (LAMC2+, KRT5+, and KRT14+), and unassigned name cells (high heat shock proteins expression), suggesting that they were cancerous cells." (PMID 35742914, 2022). "For Col1a1, we performed an analogous experiment, but this time, we examined the effect of overexpression of Col1a1 as its expression was increased in mice that underwent high-intensity aerobic exercise and decreased in cancer-bearing mice." (PMID 35801156, 2022). "Pan-cancer analysis demonstrated COL1A1 and FAM98A to have good specificity." (PMID 35151325, 2022). "Palmatine suppresses the growth of cancer cells via targeting COL1A1 in a GL1-dependent manner." (PMID 36415513, 2022). "When with chronic disease or cancer, COL1A1 and α-SMA were enhanced, but NDRG2 was suppressed." (PMID 35836988, 2022). "Col1A1 collagen demonstrates most of the fibres in cancer tissue compared to Col3A1 collagen." (PMID 34771715, 2021). "When selecting genetically modified or syngeneic transplant mouse models for preclinical tests regulating or targeting fibrillar collagens, models with a range of cancer-cell-derived COL1A1 expression need to be assessed to be representative of the wide variations seen in human PDAC." (PMID 33879793, 2021). "Human-specific qPCR indicated that the COL1A1 mRNA level from the cancer cells in the xenograft tumors was the same between mut and WT COL1A1 tumors, suggesting that the reduced ColI protein change arose post-transcriptionally, as predicted from the nature of the mutation." (PMID 33879793, 2021). "Interestingly, COL1A1 is proved to be candidate prognostic factor in several cancers such as gastric cancer." (PMID 34399848, 2021). "In the cBioPortal database, we analyzed the expression of COL1A1 across 27 kinds of cancers." (PMID 33490271, 2021). "The control of Col1a1 by EA can explain its potential to restore hematopoiesis and ameliorate the cancer inhibition of common myeloid and megakaryocytic/erythroid progenitors in cancer mice." (PMID 34552585, 2021). "Finally, high COL1A1 gene expression is a biomarker of poor outcome across a range of primary cancers." (PMID 33980846, 2021).
cancer (continued). "We then checked the expression of the canonical cell-type markers: cancer/epithelial cell marker genes (Cdh1, Krt18, and Krt5); mesenchymal cell marker genes (Col1a1, Col1a2, and Col3a1); immune cell marker genes (Ptprc, Cd68, and Csf1r); and endothelial cell marker genes (Pecam1, Emcn, and Cdh5)." (PMID 34497807, 2021). "The gene expression for COl1A1 in the cancer area was higher than Col3A1." (PMID 34771715, 2021). "Thus, the potential of EA to halt Col1a1 and abnormal collagen production can explain its potential to restore hematopoiesis and ameliorate the cancer inhibition of common myeloid and megakaryocytic/erythroid progenitors in cancer mice." (PMID 34552585, 2021). "Also, the correlations between COL1A1 and cancer immune infiltrates and the B7-CD28 family was investigated via TIMER and GEPIA." (PMID 33850663, 2021). "Therefore, COL1A1 can be viewed as not only the prognostic marker for multiple primary tumors of the digestive tract but also the prognostic marker for pan-cancer." (PMID 34395525, 2021). "We found that COL1A1 was highly expressed in various cancers." (PMID 34395525, 2021). "Moreover, we found that COL1A1 was highly expressed in other cancers in addition to gastrointestinal cancers." (PMID 34395525, 2021). "Furthermore, previous studies have identified FOXQ1, PSEN1 and COL1A1 as the major molecular targets of miR-133 underlying its inhibitory role in EMT and cancer progression 23-26." (PMID 34335946, 2021). "For cancers with high COL1A1 expression, we found a low infiltration of CD 8+ T cells by TIMER2." (PMID 34395525, 2021). "In addiation, increasing evidence confirmed that inhibition of COL1A1 could significantly suppress cancer cells proliferation, clonogenicity, and invasion, indicating that COL1A1 is a putative therapeutic target for cancer." (PMID 32850407, 2020). "Collagen type I alpha 1 (COL1A1) reportedly promotes cancer cell migration." (PMID 33665169, 2020). "Overexpression of COL1A1 was increased cancer invasion and was directly regulated by let-7i miRNA." (PMID 33080572, 2020). "With regard to the CAF model, patient-derived normal and according cancer-associated fibroblasts revealed a conserved gene expression, defined by increased transcript levels of ACTA2, COL1A1, TNC, VEGFA and ALDH1A3, with concomitant decreased expression of CAV1, CD44 and VIM in CAFs." (PMID 28372546, 2017). "COL1A1 gene methylation might be correlated with the poor prognostic characteristics of cancer-sustaining cells." (PMID 24552139, 2014). "Interestingly, high COL1A1 expression, a fibroblast marker, appears to contribute to differentiate carcinomas with significantly lower expression of this marker in adenomatous polyps and normal tissues." (PMID 25423035, 2014). "In addition, 49 genes have been reported to be relevant to immune diseases, such as CXCL12, COL1A1, MMP9, and CD36, likely reflecting an inflammatory–type response often associated with cancer." (PMID 21060876, 2010). "Finally, using qPCR, we verified that fibroblasts show an increased mesenchymal phenotype after being cocultured with cancer cells for 3 days, with increased collagen levels (COL1A1: collagen type I alpha 1 chain) compared to fibroblast monocultures (Fig. EV4D)." (PMID 40341770, 2025). "However, the specific function of COL1A1 as a cancer-promoting factor in particular tumors remains unclear." (PMID 38392197, 2024). "Notably, COL1A1 was expressed the most highly in C1 of the ColClusters in 19/26 cancer types." (PMID 37414817, 2023). "In addition to the four genes (Fos, Col1a1, Trim63, and Six2), our study identified other potential molecular factors of high-intensity aerobic exercise, which may prevent cancer proliferation." (PMID 35801156, 2022).